DPP4 (dipeptidyl peptidase 4)
Diseases named in the same sentence as DPP4 in open-access papers (continued):
Sharing a sentence is not in itself a finding about the gene and the disease.
pulmonary fibrosis (20 papers, 2017 to 2026). Chronic progressive interstitial lung disorder characterized by the replacement of the lung tissue by connective tissue, leading to progressive dyspnea, respiratory failure, or right heart failure. "Lung fibroblast activation is considered to be a major mechanism of pulmonary fibrosis, and data in this current study indicated that the number of lung fibroblasts was lower in Dpp4 deficient mice with BLM‐induced pulmonary fibrosis than that in WT mice." (PMID 36949656, 2023). "In conclusion, our study demonstrated that genetic deficiency of Dpp4 has protective effects on BLM‐induced pulmonary fibrosis in mice through a reduction in Tgfb expression levels in the lungs and direct inhibitory effects on lung fibroblast activation." (PMID 36949656, 2023). "In this study, we aimed to characterize Dpp4 deficiency in a mouse bleomycin (BLM)‐induced pulmonary fibrosis model and in cell culture systems of human lung fibroblasts (HLFs)." (PMID 36949656, 2023). "This study indicates that the genetic deficiency of DPP4 has protective effects against BLM‐induced pulmonary fibrosis, partly through the reduction in TGF‐β expression and inhibition of fibroblast activation in the lung." (PMID 36949656, 2023). "In this study, we aimed to clarify the functional roles of CD26/DPP4 in pulmonary fibrosis by focusing on fibroblast activation and EndMT using Dpp4‐deficient mice in the model of BLM‐induced pulmonary fibrosis, and in cultured human lung fibroblasts (HLFs)." (PMID 36949656, 2023). "The degree of BLM-induced lung fibrosis in this study was similar between the two genotypes, whereas previous studies have shown that intratracheally administered BLM-induced lung fibrosis in mice was attenuated by Dpp4 deficiency or treatment with the DPP4 inhibitor vildagliptin." (PMID 38255821, 2024). "This current study has advanced our understanding of the functional role of CD26/DPP4 by demonstrating that CD26/DPP4 deficiency attenuates BLM‐induced pulmonary fibrosis in mice through a reduction in TGF‐β expression and inhibition of lung fibroblast activation." (PMID 36949656, 2023). "Taken together, it might be possible in our current study that anti‐inflammatory effects of Dpp4 deficiency on BLM‐induced lung inflammation at the early stage could lead to the amelioration of pulmonary fibrosis at the later stage." (PMID 36949656, 2023). "However, the key mechanisms associated with CD26/DPP4 signaling that are involved in the pathophysiology of pulmonary fibrosis are still unclear." (PMID 36949656, 2023). "Simultaneously, a mouse model of LPS-induced pulmonary fibrosis was used to demonstrate in vivo that combined treatment with miR-23b-3p and DPP4 inhibitors can greatly alleviate pulmonary fibrosis in mice." (PMID 38150089, 2025). "DPP4 is highly expressed in fibroblasts of patients with systemic sclerosis (SSc), and DPP4 inhibitors alleviated bleomycin-induced pulmonary fibrosis." (PMID 38150089, 2025). "In our mouse model of LPS-induced pulmonary fibrosis, miR-23b-3p and a DPP4 inhibitor (sitagliptin) individually alleviated LPS-induced EndMT progression and pulmonary fibrosis, and their combined use achieved the strongest remission effect." (PMID 38150089, 2025). "Overall, the combination of miR-23b-3p and DPP4 inhibitor is more beneficial to alleviate LPS-induced pulmonary fibrosis." (PMID 38150089, 2025). "Further studies are warranted to better understand the functional role of CD26/DPP4 in pulmonary fibrosis, since multiple important questions that need to be addressed remain unanswered." (PMID 36949656, 2023). "Our study suggests that CD26/DPP4 inhibition is a potential therapeutic strategy for pulmonary fibrosis." (PMID 36949656, 2023). "The T‐cell costimulatory activity of CD26/DPP4 affects the inflammatory process in pulmonary fibrosis, although its target immune cells or pulmonary constitutive cells have not been elucidated." (PMID 36949656, 2023).
pulmonary fibrosis (continued). "Neither the number of CD31+/CD45− endothelial cells in WT mice differ after BLM challenge, nor the number of CD31+/CD45− endothelial cells differ between WT mice and Dpp4 KO with BLM‐induced pulmonary fibrosis." (PMID 36949656, 2023). "Linagliptin, a specific dipeptidyl peptidase 4 (DPP4) inhibitor, alleviated pulmonary fibrosis in a bleomycin-induced mouse model of SSc." (PMID 37833928, 2023). "In a mouse model of pulmonary fibrosis after systemic endotoxin damage, endothelial to mesenchymal transition (EndMT) was shown in endothelial cells overexpressing DPP-4(Vildagliptin), which has been reported to alleviate pulmonary fibrosis." (PMID 37025413, 2023). "Vildagliptin, another CD26/DPP4 inhibitor, ameliorates BLM‐induced pulmonary fibrosis, and Dpp4 deficiency reduces BLM‐induced fibrosis in the skin and lungs of mice, suggesting a functional participation of CD26/DPP4 in pulmonary fibrosis." (PMID 36949656, 2023). "In this study, we demonstrated that in Dpp4 KO mice BLM‐induced pulmonary fibrosis was significantly attenuated and the numbers of fibroblasts and myofibroblasts in the lungs were lower compared to those in WT mice." (PMID 36949656, 2023). "In a bleomycin-induced mouse model of lung fibrosis it was reported that pharmacological inhibition of DPP4 attenuated the development of lung fibrosis and reduced the expression of extracellular matrix proteins." (PMID 36120350, 2022). "Yang found that the DPP4 inhibitor vildagliptin can ameliorate pulmonary fibrosis by inhibiting the production of extracellular matrix (ECM) and inflammatory cells in mice." (PMID 34955820, 2021). "The current study demonstrated that in a pulmonary fibrosis murine model after systemic endotoxemic injury, EndMT was observed in endothelial cells that overexpressed DPP-4." (PMID 29037205, 2017). "The aim of this study was to investigate the anti-EndMT effects of the DPP-4 inhibitor vildagliptin in pulmonary fibrosis after systemic endotoxemic injury." (PMID 29037205, 2017). "Our in vivo and in vitro results show that in our model of pulmonary fibrosis after systemic endotoxemic injury, DPP-4 expression is upregulated in PVECs in both the presence and absence of immune cells." (PMID 29037205, 2017). "We ascertained that miR-23b-3p can inhibit EndMT in pulmonary fibrosis by targeting DPP4." (PMID 38150089, 2025). "Multiple studies have shown that DPP4 inhibitors improve pulmonary fibrosis." (PMID 38150089, 2025). "Concurrently, the expression of DPP4 was gained in LPS-induced pulmonary fibrosis blood vessels and surrounding tissues in mice, and miR-23b-3p could partially restrained the expression of DPP4 in mouse pulmonary fibrosis blood vessels and surrounding tissues." (PMID 38150089, 2025). "On the contrary, our previous study indicated that CD26/DPP4 suppression is implicated in the attenuation of pulmonary fibrosis and decreases in the numbers of fibroblasts and myofibroblasts through a TGFβ-dependent manner in BLM-induced lung fibrosis in mice." (PMID 39684311, 2024). "In addition, using Dpp4 knockout (Dpp4 KO) mice, we have revealed the functional roles of CD26/DPP4 in bleomycin-induced PH associated with interstitial lung disease, bleomycin-induced pulmonary fibrosis, and LPS-induced lung injury." (PMID 39684311, 2024). "A dipeptidyl peptidase 4 inhibitor, vildagliptin, could successfully downregulate EndoMT and reduce lung fibrosis in lipopolysaccharides-induced lung injury." (PMID 37958797, 2023). "Meanwhile, Dpp4 deficiency was unlikely to be related to EndMT regulation in mouse BLM‐induced pulmonary fibrosis." (PMID 36949656, 2023). "We aimed to investigate whether a profibrotic DPP4 phenotype is present in lung tissue from patients with idiopathic pulmonary fibrosis (IPF)." (PMID 36120350, 2022). "In animal models, DPP4 inhibitors have been shown to reduce lung fibrosis." (PMID 36120350, 2022).
pulmonary fibrosis (continued). "And it is still unclear about the effects of DPP4 inhibition in patients with pulmonary fibrosis." (PMID 34955820, 2021). "Moreover, we also found that DPP-4 expression was increased in PVECs from a post-ALI pulmonary fibrosis murine model." (PMID 29037205, 2017). "Inhibiting DPP-4 signaling by vildagliptin could ameliorate pulmonary fibrosis by downregulating EndMT in systemic LPS-induced lung injury." (PMID 29037205, 2017). "Furthermore, Masson’s trichrome staining of lung sections to evaluate fibrotic lesions showed that recurrent LPS exposure led to prominent pulmonary fibrosis, and this fibrosis was attenuated in the presence of the DPP-4 inhibitor vildagliptin." (PMID 29037205, 2017). "Based on these findings, we hypothesize that EndMT is involved in the pathogenesis of pulmonary fibrosis after systemic endotoxemic injury, which can be attenuated by the DPP-4 inhibitor vildagliptin." (PMID 29037205, 2017). "In order to evaluate whether the combination of DPP4 inhibitor and miR-23b-3p is more conducive to the remission of LPS-induced pulmonary fibrosis in vivo, we injected 100 nM sitagliptin alone or in combination with miR-23b-3p agomir into the tail vein of LPS-induced fibrotic mice." (PMID 38150089, 2025). "Thus, we propose that the DPP4 inhibitor, sitagliptin, and miR-23b-3p represent candidate therapeutics that may be used individually or in combination to alleviate pulmonary fibrosis in patients with ARDS." (PMID 38150089, 2025). "Therefore, DPP4 inhibitors may represent a promising therapeutic direction for treating EndMT-related diseases, including pulmonary fibrosis." (PMID 38150089, 2025). "However, it remains unclear how CD26/DPP4 affects mechanisms related to pulmonary fibrosis, such as fibroblast activation or mesenchymal transition." (PMID 36949656, 2023). "Therefore, DPP4 deficiency in those cell types might relate to the low expression levels of Tgfb1 and Tgfb2 in the lungs with BLM‐induced pulmonary fibrosis." (PMID 36949656, 2023). "However, whether DPP4 inhibition can ameliorate pulmonary fibrosis via an anti-senescence mechanism is unknown." (PMID 34955820, 2021). "Thus, we hypothesized that the DPP-4 inhibitor vildagliptin could attenuate pulmonary fibrosis by inhibiting EndMT." (PMID 29037205, 2017). "Additional evidence suggests that DPP-4/CD26 plays a role in the pathogenesis of various chronic fibrotic diseases, such as lung fibrosis, liver cirrhosis, cardiac fibrosis, kidney fibrosis, and systemic sclerosis." (PMID 40843763, 2025). "However, the mechanistic role of CD26/DPP4 in pulmonary fibrosis remains unclear." (PMID 36949656, 2023). "In the present study, we aimed to further investigate the presence of DPP4-expressing fibroblasts in normal and end-stage IPF human lung tissue, and the potential link between DPP4 and fibroblast activation in lung fibrosis." (PMID 36120350, 2022). "Here we showed that treatment with the DPP-4 inhibitor vildagliptin effectively suppressed EndMT and had an anti-fibrotic effect in post-ALI pulmonary fibrosis." (PMID 29037205, 2017). "CD26/DPP4 expression has been shown in the fibroblast lineage involved in the chronic fibrotic status of many organs, such as skin fibrosis in systemic sclerosis, liver cirrhosis, kidney fibrosis, and lung fibrosis." (PMID 39684311, 2024). "Nevertheless, our results suggest that the therapeutic effect observed in animal models of lung fibrosis is unlikely to originate from inhibition of DPP4 on tissue-resident THY1+ fibroblasts." (PMID 36120350, 2022). "Still, the cells directly affected by DPP4 inhibition in lung fibrosis remain unclear and the specific role of DPP4 on human lung fibroblasts in IPF has not been investigated." (PMID 36120350, 2022). "First, we have not examined whether other DPP-4 inhibitors could be beneficial for inhibiting post-ALI pulmonary fibrosis in vivo." (PMID 29037205, 2017).
chronic obstructive pulmonary disease (19 papers, 2017 to 2024). A chronic and progressive lung disorder characterized by the loss of elasticity of the bronchial tree and the air sacs, destruction of the air sacs wall, thickening of the bronchial wall, and mucous accumulation in the bronchial tree. "DPP4 mRNA and protein expression are inversely correlated with lung function and diffusing capacity parameters, which can partially explain the fact that smokers and chronic obstructive pulmonary disease (COPD) patients seem to be more susceptible to coronaviruses." (PMID 32764275, 2020). "Two of the risk factors, i.e., smoking and chronic obstructive pulmonary disease (COPD), have been shown to upregulate DPP4 expression in the lungs, suggesting DPP4 as a possible reason for intraspecies variation observed among MERS-CoV patients." (PMID 30893947, 2019). "This might explain why chronic obstructive pulmonary disease (COPD) patients attacked by MERS‐CoV had poor outcomes, since the expression of DPP4 was predominantly upregulated on type I pneumocytes in such patients." (PMID 33173860, 2020).
Nephropathy (19 papers, 2013 to 2025). A nonspecific term referring to disease or damage of the kidneys. "First, activation of RAS induced by low salt and activation of TGFβ1 induced by CyA may increase DPP-4 activity, but tubulointerstitial injury and associated cell loss in proximal tubule cells (PTCs) is the prominent feature of CyA-induced nephropathy." (PMID 33803842, 2021). "Of relevance is that the characteristics of DPP-4 inhibitor-induced renal injury seen in this patient differ from those seen in typical T2D nephropathy." (PMID 38055184, 2024). "Compared to other microvascular complications, nephropathy is considered the most studied in major trials on DPP-4 inhibitors including TECOS, SAVOR-TIMI, MARLINA, and CARMELINA." (PMID 32190049, 2020). "In contrast, MERS-CoV binds a different cell receptor, i.e., dipeptidyl dipeptidase 4 (DPP4 or CD26), which is also expressed by various renal cells, justifying the infiltration of the virus and the consequent kidney damage." (PMID 32560340, 2020). "Linagliptin also increased renal SDF-1 expression and plasma SDF-1 levels in rats with obesity-related nephropathy, with concomitant reductions in renal DPP-4 activity, damage to the glomerular filtration barrier, and proteinuria." (PMID 29491123, 2018). "This corroborated our previous findings that DPP4 influenced the extent of kidney damage during IR injury." (PMID 28903385, 2017). "Therefore, we investigated the role of a novel DPP-4 inhibitor, DA-1229, on the progression of renal disease in an experimental CyA-induced nephropathy model." (PMID 33803842, 2021). "However, in rats with obesity-related nephropathy, linagliptin reduced damage to the glomerular filtration barrier and proteinuria, while reducing DPP-4 activity in kidney tissue and increasing plasma levels of GLP-1 and SDF-1α." (PMID 29491123, 2018). "A study showed that treatment of rats with DN with linagliptin, a DPP-4 inhibitor, reduced proteinuria and slowed fibrotic kidney damage without affecting blood glucose levels." (PMID 36249783, 2022). "In addition, dipeptidyl peptidase 4 (DPP-4), a drug that inhibits the degradation of GLP-1, reduces kidney damage through antiapoptotic, immunological, and antioxidative changes." (PMID 34335269, 2021).
steatosis (19 papers, 2017 to 2026). Increased lipid within the cytoplasm of cells. "In addition to steatosis, other liver-specific insults associated with elevated circulating DPP4 include HCV." (PMID 36472923, 2023). "Increased DPP4 expression in the liver positively correlates with the degree of steatosis and NAFLD." (PMID 36472923, 2023). "The DPP-4 inhibitor, sitagliptin, has been demonstrated to attenuate steatosis in a diet-induced NAFLD model and ameliorate NAFLD activity score (NAS) by improving steatosis and ballooning in NAFLD patients." (PMID 35163991, 2022). "As observed for circulating DPP4 activity, also plasma DPP4 concentration positively correlated with steatosis grade (r = 0.71, p = 0.032), lobular inflammation (r = 0.5, p = 0.024) and ALT levels (r = 0.48, p = 0.03)." (PMID 32852705, 2021). "In NAFLD patients, both plasma DPP4 activity and concentration linearly correlated with hepatic inflammation and steatosis grade at the liver biopsy, and with clinical markers of hepatic damage." (PMID 32852705, 2021). "Empirical evidence suggests that sitagliptin might improve steatosis by suppressing lipogenic and gluconeogenic pathways through the inhibitation of DPP-4 and increasing levels of biological activity of GLP-1 and GIP." (PMID 35966875, 2022). "In our research, both DPP4 activity and concentration were associated to more severe steatosis grade and inflammation at the biopsy whereas hepatic DPP4 expression was not influenced by liver damage in the course of NAFLD/NASH." (PMID 32852705, 2021). "Therefore, we investigated the effects of hepatic dpp4 silencing on plasma lipids and steatosis in liver." (PMID 31794591, 2019). "Furthermore, the intensity of immunofixation of DPP4 in liver and its serum activity correlated with the histological grade of steatosis and NASH." (PMID 28450900, 2017). "Hence, besides confirming that NAFLD individuals display greater circulating DPP4 activity, we demonstrated the existence of a correlation between plasma sDPP4 and the steatosis grade, lobular inflammation, and ALT levels in severely obese individuals with biopsy-proven NAFLD." (PMID 36140405, 2022). "The expression of TMPRSS2 remained unchanged in MASLD, whereas the MERS-CoV receptor dipeptidyl peptidase 4 (DPP4) and the SARS-CoV-2 coreceptor CLEC4M were lower in steatosis and steatohepatitis, with respect to controls." (PMID 38074511, 2024). "Surprisingly, however, complete genetic elimination of Dpp4 or hepatocyte-specific elimination in aged mice resulted in no changes in liver enzymes and the degree of steatosis." (PMID 36472923, 2023). "In non-steatotic livers, hepatic levels of DPP4 were more elevated in the CD group than in the Sham group, whereas, in the presence of steatosis, DPP4 levels in the livers of the CD group were lower after CD induction than those observed in Sham group." (PMID 31835410, 2019). "Shirakawa and collaborators explored the effects of des-fluoro-sitagliptin treatment on hepatic steatosis in animal models fed with a sucrose-rich diet and showed that DPP4 inhibition decreased the grade of steatosis at the liver histology, without impacting the overall liver weight." (PMID 36140405, 2022). "NAFLD patients had significantly higher circulating DPP4 activity than no-NAFLD in both the obese and non-obese cohorts; plasma DPP4 activity and levels linearly correlated with steatosis grade and inflammation at the liver biopsy." (PMID 32852705, 2021).